FOXP3 (forkhead box P3)
Diseases named in the same sentence as FOXP3 in open-access papers (continued):
Sharing a sentence is not in itself a finding about the gene and the disease.
Arthritis (continued). "In the arthritis-related studies, CFA/I fimbriae elicited a heterogeneous population of CD39+ Tregs, where a portion were IL-10+ Foxp3+ and another portion being TGF-β+ Foxp3−." (PMID 33823920, 2021). "Of notice, numbers of total T cells (TCRβ+ cells) and CD4+ T cells and of total cTregs and RORγt-expressing cTregs — but not of CD4+IL-17+FoxP3– (cTh17) cells — were expanded in the colons of mice with established versus early DSS-induced arthritis." (PMID 33055428, 2020). "Whereas, neither CD4+CD25+Foxp3+Helios+ nor CCR6+ response to α-glucosidase inhibitors was observed in the groups when treatment started at arthritis induction." (PMID 32116681, 2019). "This study is an early demonstration of CM-MSC induced increases in Treg induction and expression of FOXP3, alongside positive adjustment of the Treg:Th17 balance, without Th17 or Th2 cell induction at 3 days post-arthritis induction in AIA mice." (PMID 29269885, 2017). "In proteoglycan-induced arthritis (PGIA), an experimental murine model of arthritis, Treg cell percentage was elevated in B cell-depleted mice, compared to control treated mice that exhibited a higher proportion of CD4+ T cells expressing Foxp3 and CD25." (PMID 27847522, 2016). "However, to our knowledge, this is the first study to address, in-depth, the use of the Foxp3-DTRe-GFP mouse for Treg depletion in experimental arthritis and the first to use the Foxp3-DTR-eGFP mouse on a B6 background in experimental arthritis." (PMID 26822477, 2016). "The impaired expression of CD39 in Foxp3+ Treg cells of MLDSTZ + IL-35 treated mice further support this hypothesis, since IL-35 has been shown to induce CD39 expression in order to dampen arthritis by inducing Treg cells." (PMID 26224624, 2015). "Indeed, 1-MT abrogated the increase in the proportion of CD4+CD25+ Foxp3+ T cells induced by CD11b+ DC from EGCG-fed CIA mice which correlated with arthritis scores." (PMID 26379475, 2015). "Late during the course of arthritis (day 42) the proportion of CD19+ MHCII+ B cells was decreased in lymph nodes in LNT-IL-10 mice whereas the proportion of CD4+ Foxp3+ regulatory T cells was not affected." (PMID 23166758, 2012). "The transfer of exogenous CD4+CD25+ T cells or Foxp3+-transduced CD4+ cells from healthy mice into pre-arthritic mice inhibits the development of arthritis, suggesting a regulatory role for Treg cells in the development of arthritis." (PMID 21483764, 2011). "The proportion of Foxp3+ Treg cells is increased in mice with type II collagen–induced arthritis, but Foxp3+ Treg cells do not completely prevent the development of arthritis." (PMID 21483764, 2011). "Notably, the percentage of CD4+ T cells expressing FoxP3 was not significantly correlated with arthritis score or significantly increased with TRI MP treatment." (PMID 32966314, 2020). "These induced hCD8+Tregs expressed CD103 and Foxp3, did not secrete IL-17A, were stable in inflammatory conditions, had potent suppressive ability, and could alleviate collagen-induced arthritis." (PMID 30915372, 2019). "Interestingly, the induction of arthritis in mice did not increase FOXP3 mRNA expression in the draining lymph nodes of animals that received vehicle as treatment." (PMID 27872515, 2016). "However there was no remarkable increase in FoxP3+ Treg in ASCIA mice without arthritis compared to CIA or ESCIA mice with arthritis." (PMID 20537152, 2010). "FOXP3 (Treg) and GATA3 (Th2) mRNA expression levels were not significantly different between the SCW-arthritis groups." (PMID 22719976, 2012).
diabetes (106 papers, 2006 to 2026). "The demonstration of the importance of regulation in control of disease was shown in NOD mice deficient in functional FoxP3, which developed diabetes at a faster rate than wild-type control mice." (PMID 23555752, 2013). "Immunodysregulation, Polyendocrinopathy Enteropathy X-linked syndrome is due to a mutation in FOXP3 (Forkhead Box P3, a master regulator of Treg function) and is characterized by a triad of intractable diarrhea, type 1 diabetes mellitus (T1DM), and eczema, as well as other autoimmune features." (PMID 34277517, 2021). "Treg cells are a subset of CD4+ T cells that express IL-2 receptor alpha chain CD25 and FOXP3 transcription factor to maintain immune tolerance during diabetes." (PMID 41948347, 2026). "Genetic screening identified, in 2 patients with diabetes onset before 1 year of age, 2 likely pathogenic novel variants affecting canonical splicing sites: c.286-12_290del in STAT5B and c.-22-2delA in FOXP3." (PMID 39870583, 2025). "The obtained findings show that the lower proportions of IL-2-expressing ILC3 and FoxP3+ Treg in SILP coincided with diabetes progression and severity." (PMID 37110604, 2023). "FOXP3 also plays a key role in Type 2 diabetes mellitus (T2DM) and its complications, because the disease usually involves chronic low-grade inflammatory disorders and is associated with long-term immune system imbalance." (PMID 36717877, 2023). "Data obtained in this study show that the transition from prediabetes to diabetes in NOD mice is associated with the decrease in IL-2-producing ILC3 and FoxP3+ Treg in the SILP." (PMID 37110604, 2023). "Nevertheless, using immunofluorescent staining of pancreas tissue either at the time of diabetes diagnosis or 30 days after transfer, we found FOXP3+ InsB-g7 CAR Tregs in close islet proximity, in peri-insulitis, and within islets." (PMID 37561596, 2023). "We then looked at regulatory T cells, because other laboratories previously reported an increase in CD4+ CD25+ FoxP3+ “Tregs” in NOD mice as diabetes developed." (PMID 36291615, 2022). "As an example, administration of the AHR agonist TCDD prevented diabetes onset in NOD mice by increasing the frequency of Foxp3+T cells in pancreatic lymph nodes." (PMID 35757772, 2022). "We have shown recently that the application of exogenous IL-33 given from the beginning of MLD–STZ diabetes induction attenuates the development of diabetes, by increasing the presence of regulatory FoxP3+ ST2+ cells." (PMID 34803672, 2021). "In the present study, we analyzed the levels of Tregs in LN of NOD mice at different ages before and after diabetes onset in our colony using Foxp3 as a marker." (PMID 31281853, 2019). "Instead, antigen specific FoxP3 transduced cells were highly effective at reversing recent onset diabetes." (PMID 30842776, 2019). "For example, antigen-specific Foxp3+ regulatory T cells have been shown to suppress auto-immune diabetes and graft rejection." (PMID 31921109, 2019). "For example, hemizygous mutations in FOXP3 cause immunodysregulation, polyendocrinopathy, enteropathy, X-linked (IPEX) syndrome, which presents in the neonatal period with diabetes, protein-losing enteropathy and severe eczema." (PMID 29417186, 2018). "In NOD mice, low-dose IL-2 prevents clinical onset and reverses diabetes via an expanded pool of Foxp3+ Treg in the islets and draining pancreatic lymph nodes." (PMID 30166987, 2018). "Prevention of diabetes can be tested by mating of floxed NOD-3×FLAG-mIR/MFM mice with commercially available NOD.FoxP3-cre mice (The Jackson Laboratory) to test the ability of T-regulatory cells to be delivered therapeutically via IR based chemotaxis." (PMID 29862308, 2018). "This combination expands the frequency of Foxp3+Treg in a peptide-specific manner that results in prevention of diabetes in NOD mice." (PMID 30166987, 2018). "In MLD-STZ diabetes model we showed that resistance to disease in BALB/C mice depends partially on CD4+CD25+Foxp3+ cells." (PMID 30498495, 2018).
diabetes (continued). "In different murine models of T1D, anti-CD20 mAb suppresses the progression of β cell autoimmunity as well as reverses diabetes onset, by promoting Foxp3+Treg and regulatory B cell populations." (PMID 30166987, 2018). "Mice protected from diabetes by BTZ in vivo also displayed increased percentages of Foxp3+CD4+ and IDO1 protein expression in both pLNs and pancreata, and an increased systemic Kyn/Trp ratio." (PMID 28450863, 2017). "T regulatory cells (Treg; FOXP3+ cells) mediate inflammatory resolution and retard the progression of diabetes." (PMID 25352830, 2014). "Diabetes incidence in mice receiving Foxp3+ cells mirrored that of separate sets of control mice that serve to determine cumulative diabetes incidence in our NOD colony." (PMID 25393309, 2014). "It is possible that the increase in Foxp3+ cells aids in the prevention of diabetes progression in recipients receiving NOD-Alox15null donor cells." (PMID 23437231, 2013). "For example, TCDD was shown to suppress diabetes in NOD mice by potentially increasing Foxp3+ T cells in pancreatic lymph nodes." (PMID 21858153, 2011). "These mice are deprived of natural CD25+FoxP3+ natural Tregs and they exhibit exacerbated Th1 responses and accelerated diabetes." (PMID 19936238, 2009). "Specific ablation of PD‐1 from Foxp3+ Tregs was shown to protect from diabetes in NOD mice." (PMID 40623940, 2025). "The indication arises that performing FOXP3 gene sequencing in males with a history of neonatal diabetes, even in the absence of autoimmune-associated conditions at present, is warranted." (PMID 39372653, 2024). "We aimed to investigate if diagnosing IPEX at presentation with isolated diabetes could allow for effective monitoring of disease progression and assess whether TSDR analysis can aid FOXP3 variant classification and predict disease course." (PMID 36600150, 2023). "Additionally, this work demonstrated that RAS inhibition improves Tregs’ immunosuppressive function in a FOXP3-dependent manner, which allowed RAS-deficient Tregs to prevent the development of diabetes in a mouse model of the disease by up to 70%." (PMID 38096229, 2023). "Increased activation of FOXP3 has been shown to prevent diabetes in NOD mice." (PMID 37296126, 2023). "Moreover, Foxp3+ Tregs maintained amphiregulin production at diabetes onset, suggesting that islet-resident Tregs retain the capacity to produce amphiregulin throughout the course of disease." (PMID 37903947, 2023). "In fact, Idd1 was shown to confer most of the diabetes risk, but not to be sufficient to precipitate diabetes in Foxp3+ Treg cell-proficient NOD mice." (PMID 38164128, 2023). "Experimental evidence has confirmed its significant difference in the gut of diabetic mice may contribute to the pathogenesis of T1D by decreasing FOXP3-positive regulatory T cells (Tregs) that protect against diabetes." (PMID 34777313, 2021). "This treatment prevented diabetes development by induction of Ag-specific FoxP3+ Tregs." (PMID 33133064, 2020). "Cotransfer of diabetogenic T cells and splenocytes of NOD mice treated with RGI-3100-iB, but not liposomal α-GalCer encapsulating an unrelated peptide, to NOD-SCID mice resulted in the prevention of diabetes and elevation of Foxp3 mRNA expression in the islets." (PMID 31781669, 2019). "Finally, i.p. application of GM-CSF + IL-10-generated (without MPLA activation) tolDCs loaded with immunodominant insulin B chain peptides prevented diabetes in NOD mice by in situ induction of Foxp3+ Tregs, when cultured in autologous mouse serum." (PMID 29503651, 2018). "Notably, treatment of NOD mice at a late preclinical T1D stage with AAViP-IL2 results in the expansion of islet-resident Foxp3+Treg, suppression of β cell-specific Teff, and prevention of diabetes onset." (PMID 30166987, 2018).
diabetes (continued). "They identified a panel of six genes, including FOXP3, TNFRSF1B (CD120b) and LRRC32 (GARP), which were directly linked to Treg function and stability and were differentially expressed in Tregs from individuals with diabetes." (PMID 28770318, 2017). "This study shows that the requirements for the interaction of FoxP3 with co-factors, which governs its regulatory ability, differ not only between natural and inducible Treg cells but also between animal models of diseases such as diabetes and EAE." (PMID 23593464, 2013). "This could lead to upregulation of CD4+ CD25+ Foxp3+ regulatory T cells, the process connected with autoimmune nature of diabetes mellitus." (PMID 24069226, 2013). "Moreover, in a mouse model of autoimmune diabetes (the BDC2.5/NOD TCR tg mice) co-transfer of CD4+ T cells expressing Foxp3 mutants were unable to suppress diabetes induction, whereas cells expressing wild type Foxp3 were able to suppress." (PMID 22764736, 2012). "The ratio of Foxp3+ Tregs/IFN-γ+ Teffs may contribute to the delay of diabetes." (PMID 36032077, 2022). "Activation of the ARNTL could prevent diabetes by increasing Foxp3+ regulatory T cells." (PMID 28676675, 2017). "Interestingly, in our study IL-35 administration reduced the numbers of Foxp3+Nrp1+ cells, which may suggest a protective role of IL-35 also in other aspects of diabetes." (PMID 26224624, 2015). "It has also been observed that diabetes-prone BioBreeding (BBdp) rats housed in specific germ-free (GF) conditions and weaned onto cereal diets displayed an upregulation of the interferon gamma (Ifng) and interleukin 15 (Il15) genes and a downregulation of the forkhead box P3 (Foxp3) gene." (PMID 25421534, 2014). "Several nonmutually exclusive mechanisms may account for the absence of overt diabetes in Foxp3-deficient mice, which includes premature death and altered T cell repertoire selection due to severe defects in thymic T cell development." (PMID 23691523, 2013). "The upregulation of Foxp3, CD103 and granzyme B expression may reflect restoration of a fully activated regulatory cell population, which may be crucial for the regulation of pathogenic cells and prevention of diabetes development." (PMID 19011680, 2008). "Low-dose IL-2 significantly expanded CD4+CD25+Foxp3+ Tregs in the blood and spleen of mouse models of OIR and diabetes (1.4- to 1.9-fold increase, p<0.01)." (PMID 40133487, 2025). "Our previous data showed that both Foxp3 mRNA levels and Treg cell proportions were elevated in the pancreas and spleen of STZ mice when diabetes was established." (PMID 38424350, 2024). "We observed an increased prevalence of Foxp3+ Tregs together with a decrease in TH1 cytokine levels in successfully-treated, diabetes-free mice, especially in PLN, when injected into the abdominal region overlying the expected location of the pancreas." (PMID 33763059, 2021). "In the current study, we have found a correlation between low percentages of Foxp3-expressing CD4+ Tregs in NOD mice and the high incidence of diabetes (90-100%) in our colony." (PMID 31281853, 2019). "In contrast, at ~9-10 weeks of age (i.e., shortly before diabetes onset), the percentages of CD4+Foxp3+ cells were significantly lower in NOD mice than B6 controls." (PMID 31281853, 2019). "Our study also showed that the exogenous IL-33 leads to the expansion of CD11c+IL-2+ cells and increased number of CD4+Foxp3+ST2+ immunoregulatory cells that suppress the development of diabetes in mice treated with IL-33 during the induction of the disease." (PMID 30498495, 2018). "It has been reported that exogenous polyclonal iTregs retain Foxp3 expression and immune-suppressive activity in mouse models of SLE, diabetes, and RA." (PMID 25405209, 2014). "In summary, this study demonstrates that low doses of orally administered silkworm-produced CTB-Ins-GFP protein can effectively suppress the development of diabetes in NOD mice, where the treatment function involves inducing CD4+CD25+Foxp3+ Treg cells." (PMID 21765853, 2011).
diabetes (continued). "In diabetic mice, low-dose IL-2 increased Foxp3+ cells in the retina compared with non-diabetic and diabetic controls (untreated diabetes: 3.01 ± 0.41 vs diabetes + low-dose Il-2: 5.90 ± 1.25 cells per field, p<0.001)." (PMID 40133487, 2025). "As FOXP3 + T cells can suppress many types of immune cells, such as CD4 + T cells and NK cells, they have the potential to suppress a wide spectrum of immunological diseases, such as diabetes." (PMID 37296126, 2023). "Administration of hybrid insulin peptide-coupled PLG NPs was found to prevent diabetes by impairing the ability of CD4+ T cells to produce proinflammatory cytokines through induction of anergy, leading to an increase in the ratio of Foxp3+ regulatory T cells to IFN-γ+ effector T cells." (PMID 35336018, 2022). "Here, we show that anti-CD3 mAb therapy in Treg cell-depleted NOD.DEREG mice potently interfered with diabetes development, probably by mechanisms independent of Foxp3+ Treg cells." (PMID 34447385, 2021). "Data by others indicate that nanoparticle formulations of RA and TGFβ can convert T-cells into Tregs, and when administered (nanoparticles or hydrogels) into NOD female mice, they foster an increase in the number of Foxp3+ Tregs inside the PLN and/or the pancreata of diabetes-free mice." (PMID 33763059, 2021). "Increased FOXP3+ cell number has also been found in pancreatic islets after the treatment of NOD mice with Akkermansia, which was accompanied by delayed development of diabetes." (PMID 33013834, 2020). "However, significant decreases in this population were found at 9 weeks of age, i.e., at approximately the age that lower percentages of CD4+Foxp3+ cells are found in the periphery in NOD mice, and shortly before the mice begin to develop full-blown diabetes." (PMID 31281853, 2019). "Using CRISPR-Cas9 genome editing technology, we removed the Foxp3 CNS1 region in the non-obese diabetic (NOD) mouse model of spontaneous type 1 diabetes mellitus (T1D) to determine if pTregs contribute to autoimmune regulation." (PMID 31647813, 2019). "More recently, in an elegant study, Pesenacker and colleagues examined the expression of a panel of FOXP3+ Treg-specific transcripts in Tregs freshly isolated from individuals with recent-onset type 1 diabetes and well-matched individuals without diabetes." (PMID 28770318, 2017). "One early report suggested that FOXP3+ Tregs (defined as CD4+CD25+ T cells) were decreased in frequency in individuals with type 1 diabetes (vs control individuals without diabetes)." (PMID 28770318, 2017). "Most interestingly, acute depletion of Foxp3+ CD25+ Treg cells by anti-CD25 (PC61) antibody injections, but not isotype antibody injections, into vaccinated/ppins-primed PD-L1−/− mice resulted in diabetes development." (PMID 27406624, 2016). "A pCI/ppinsΔA12-21 vector (lacking the critical Kb/A12-21 epitope) did not induce autoimmune diabetes but elicited a systemic Foxp3+ CD25+ Treg cell immunity that suppressed diabetes induction by a subsequent injection of the diabetogenic pCI/ppins." (PMID 27406624, 2016). "We showed that a ppinsΔA12-21 antigen (lacking the critical Kb/A12-21 epitope) primed regulatory T cells with a TGF-β+ Foxp3+ CD25+ CD4+ signature and efficiently suppressed CD8+ T cell-mediated diabetes development by a subsequent injection of the diabetogenic pCI/ppins vector." (PMID 27406624, 2016). "After tolerogenic DEC-205+ dendritic cell vaccination to promote proinsulin-reactive Foxp3+ Treg cell activity, cotransfer of total spleen cells from autoimmune protected NOD donors can delay the onset of diabetogenic splenocyte-mediated diabetes in NOD.Rag1−/− recipients." (PMID 23691523, 2013). "Our study uncovered several novel features of AG490 such as prevention of diabetes, initiation of remission in newly diagnosed NOD mice and in pharmacological induced diabetic mice, increasing number of Foxp3 regulatory T-cells and probably generation of regulatory DC." (PMID 22615750, 2012).